CXCL1 (C-X-C motif chemokine ligand 1)
Diseases named in the same sentence as CXCL1 in open-access papers (continued):
Sharing a sentence is not in itself a finding about the gene and the disease.
cancer (continued). "While we specifically focused on ovarian HGSC, our patient data analyses reveal that CXCL1 is highly expressed in several human cancers, making it an attractive potential therapeutic target to prevent invasion and metastasis in many cancer types." (PMID 33126568, 2020). "Most of the genes in the subnetworks were inflammatory cytokines and participated in TNF signaling pathways and pathways in cancer, such as Ccl2, Ccl20, Csf1, Cx3cl1, Cxcl1, Cxcl3, Il6, Birc3, Map3k8, Nos2, Nfkb2, Tnfrsf1b, and Vcam1." (PMID 33042984, 2020). "Some of these chemokines such as CXCL1, CXCL5, CXCL6 and CXCL8 are produced at high levels by tumors cells, whereas some are also produced by blood cells, cancer associated fibroblasts or endothelial cells." (PMID 32727083, 2020). "In the case of cancer, IL-8 (as well as CXCL1 or CXCL2) is known to be involved in angiogenesis and the recruitment and activation of immune cells." (PMID 31504643, 2020). "The prostate stromal cells are also known to secrete proinflammatory and cancer-promoting chemokines such as CXCL-1, CXCL-2, CXCL-3, and interleukin (IL)-8, which are the key regulators of cellular plasticity, culminating in inflammation, and PCa progression." (PMID 32754615, 2020). "Another study showed that IL-1β expressed in OSCC cells leads to CXCL1 production by CAFs, which in turn promotes cancer cell migration." (PMID 32635472, 2020). "Cancer cells release CXCL1 and CXCL2 chemokines, which in turn induce the generation of mo-MDSCs as a bone marrow cell subpopulation." (PMID 32488850, 2020). "In ER-negative breast cancer, CXCL1 enhances cancer cell migration and invasion through an ERK/MMP2/MMP9 signal pathway." (PMID 33256011, 2020). "We found that vessel growth and migration of human vascular endothelial cells (HUVECs) was promoted by conditioned medium from HS578T-tet-off-HEYL carcinoma cells, but was blocked by neutralizing antibodies against CXCL1/2/3." (PMID 33520697, 2020). "Most members of the chemokine family, including CXCL1, CXCL2, CXCL5, CXCL9, CXCL10 and CXCL13, where they are secreted by cancer or stromal cells, such as cancer-associated fibroblasts (CAFs) and dendritic cells (DCs)." (PMID 30925930, 2019). "Here, we observed that the serum levels of various chemokines, including CCL19, IL-8, CXCL1, CXCL12, and RANTEs, the latter of which has been associated with the recruitment of Tregs in cancer patients, were increased in BC patients." (PMID 30718502, 2019). "The chemokines (CXCL1, 2, 5, and 8) upregulated by cancer-derived VEGF-C in LECs are all cognate ligands of CXCR2." (PMID 31390756, 2019). "The results indicated that the expression of CXCL1 in cancer tissues was apparently higher than that of normal tissue." (PMID 31998654, 2019). "Accumulating evidence has proved that CXCL1 plays an important role in the development of various malignant tumors." (PMID 31998654, 2019). "The expression of CXCL1, CXCL3, CXCL2, CCL20, and IL6 are enriched in residual cancer and are associated with lesser response the chemotherapy when highly expressed at baseline." (PMID 30967156, 2019). "The CXCL1 protein secreted by cancer cell lines was detected by SearchLight proteome array and human cytokine antibody array." (PMID 31998654, 2019). "In ER-negative breast cancer, CXCL1 is highly expressed and stimulates cancer cell migration and invasion via activating the ERK-MMP2/9 signaling pathway." (PMID 31998654, 2019). "In this study, we found that CXCL1 is not only released from malignant cells, but also secreted from cancer-conditioned DCs." (PMID 30115896, 2018). "The findings reported here not only introduce a novel mechanism of immunosuppression, but also provide preliminary evidence of the potential utility of CXCL1 inhibition as a therapeutic strategy in fighting cancer." (PMID 30115896, 2018).
cancer (continued). "Despite that both IL-6 and CXCL1 induced the senescent phenotype of CAFs, CXCL1 secretion showed a cancer-specific response to transform NOFs into CAFs in OSCC, whereas IL-6 secretion was eventuated by common co-culture condition." (PMID 29360827, 2018). "Unbiased analyses identified cancer-elaborated CXCL1/PPBP, potent myeloid cell chemoattractants that drive inflammation and metastasis via CXCR1/CXCR2 on host cells, as the transcriptional targets of IL-1β-fostered KRAS-IKKα addiction." (PMID 29445180, 2018). "Previous studies have indicated that multiple mechanisms are involved in CXCL1-induced cancer metastasis." (PMID 30158589, 2018). "The previous studies demonstrated that CAFs-derived CXCL1 can be a therapeutic target in cancer therapy." (PMID 29360827, 2018). "PGE2 controls the local recruitment of MDSCs by regulating their expression of CXCL12 and CXCR4 and stimulates tumoral secretion of the pro-angiogenic CXCL1, thus promoting micro-vessel formation and cancer progression." (PMID 30591657, 2018). "Our work shows that IL-1β derived from inflammatory UC-MSCs induces the production of downstream cytokines CCL2, CXCL1, IL-6, and IL-8 in an autocrine manner, which promotes stem cell-like characteristics of cocultured cancer cells." (PMID 29670904, 2018). "BC cells that overexpress CXCL1 and 2 are primed for survival at metastatic sites, which links cancer chemoresistance." (PMID 30034618, 2018). "Several clinical studies indicate that overexpression of inflammatory cytokines, such as IL-1, IL8, IL6 or CXCL1, correlates with cancer progression and decreased response to EGFR targeting therapy." (PMID 30261609, 2018). "With regard to CXCL1, several studies have highlighted its significant role in mediating the communication between cancer cells and TME." (PMID 30158589, 2018). "Elevated chemokine (C-X-C motif) ligand 1 (CXCL1) levels are found in CRC, and these increased levels are positively associated with cancer stage, metastasis and poor survival rates." (PMID 30115896, 2018). "These endothelial cells also secrete TNFα which helps stimulate cancer cell secretion of CXCL1/2 resulting in increases in cancer cell survival." (PMID 29881724, 2018). "This is the first report that demonstrates clinical significance CXCL1 expression of cancer cells and CXCR2 expression of fibroblasts." (PMID 28575019, 2017). "CXCL-1 abolished the ability of XIAOPI formula to inhibit metastasis, indicating that CXCL-1 is a critical mediator responsible for the anti-cancer activities of the formula." (PMID 29109519, 2017). "In the present study, the Kaplan-Meier survival curves for the patients revealed that those with CXCL1 expression in cancer cells and those with CXCR2 expression in stromal cells had poorer survival rates than the patients without either of these expressions." (PMID 28575019, 2017). "The patients who were positive for both CXCL1 in cancer cells and CXCR2 in stromal cells (n = 74) had significantly worst prognoses in comparison with the other groups." (PMID 28575019, 2017). "Dysregulated expression of CXCL1 and IL-6 have also been attributed to enhanced angiogenesis and tumorigenesis in cancer cells via constitutive activation of NF-κB." (PMID 28445977, 2017). "We further validated the importance of CXCL-1 in mediating the anti-cancer effects of XIAOPI formula." (PMID 29109519, 2017). "CXCL1, MMP9, IL1B, WNT7A, and CCL2 were associated with cancer malignant characteristics which were remarkably decreased in Top 10 list." (PMID 28881805, 2017). "The expression of CXCL1 in cancer cells was correlated with T invasion (T2–T4), lymph node metastasis, lymphatic invasion, venous invasion, peritoneal cytology, peritoneal metastasis and CXCR2 expression in stromal cells." (PMID 28575019, 2017). "In order to validate the critical role of CXCL-1 in mediating the anti-cancer activities of XIAOPI formula, we carried out in vitro verification experiments using MDA-MB-231 cells." (PMID 29109519, 2017).
cancer (continued). "On the other hand, the protein expression of both CXCL1 in cancer cells and CXCR2 in stromal cells was significantly correlated with overall survival." (PMID 28575019, 2017). "It was reported that the chemokine (C-X-C motif) ligand 1 (CXCL1) from cancer cells stimulated the recruitment of bone marrow-derived mesenchymal cells (BM-MCs) into tumor stroma via chemokine (C-X-C motif) receptor 2 (CXCR2) signaling." (PMID 28575019, 2017). "In both infection and cancer microenvironment, CXCL1 is elevated by various stress-inducing factors, including PGE2." (PMID 27446967, 2016). "Next, we performed experiments to confirm that CXCL1 secreted by cancer cells has a chemotactic activity on ASCs." (PMID 27241286, 2016). "In all three patients who progressed for whom tissue was available, strong CXCL1 expression in cancer cells was observed in all cases and infiltrating CXCR1-bright cells in two of three cases." (PMID 27241286, 2016). "Altogether, these evidences confirm that CXCL1/GRO-α plays an important role in various malignant tumors through its involvement in tumor generation, proliferation, migration, and invasion." (PMID 27472713, 2016). "As for cancer cell migration, senescent HPMCs stimulated this process via CXCL1 and TGF-β1 (in A2780 cultures); CXCL1, CXCL8, and fibronectin in OVCAR-3 cells; and CXCL8 and IL-6 in SKOV-3 cells." (PMID 28032864, 2016). "In fact, Sema3c, Id1, Cxcl1 and Ctgf, which are upregulated in a variety of cancer types, were downregulated upon Pdrg1 silencing." (PMID 27548429, 2016). "CXCL1 is a chemokine acting as an oncogenic factor in several cancers, such as prostate cancer, melanomas, and gliomas." (PMID 26462152, 2015). "CXCL1/2 promote recruitment of G-MDSCs which secrete S100A8/9, which results in amplifying the CXCL1/2-S100A8/9 loop and causing increased cancer cell survival, metastasis, and chemoresistance." (PMID 26078490, 2015). "In this way, our observation of the fast up-regulation of CXCL8, CXCL6 and CXCL1 by 1,25(OH)2D3 provides an additional aspect to the effects of the nuclear hormone on the immune response with impact on cancer immunology." (PMID 24250750, 2013). "TNF-alpha increases CXCL1 and CXCL2 expression in cancer cells and amplifies the CXCL1/2 S100A8/9 loop, which causes chemoresistance." (PMID 25562519, 2013). "Further studies are warranted to define the role CXCL1 plays in bladder carcinogenesis and progression." (PMID 23815949, 2013). "In conclusion, in the present study we demonstrate that VEGF can induce CXCL1 mRNA and protein expression in A549 carcinoma epithelial cells through VEGFR, JNK and PI-3K-dependent pathway." (PMID 23665907, 2013). "In summary, we provide here evidence showing JNK activation for VEGF-induced CXCL1 DNA transcription and PI-3K pathway for extracellular CXCL1 release in human carcinoma epithelial cells." (PMID 23665907, 2013). "In this study we screened several mediators/growth factors on CXCL1 release in human carcinoma epithelial cells." (PMID 23665907, 2013). "Consistently, in IHC analysis, a positive significant correlation was found exclusively between the scores of GLO1 and CXCL1 or CXCR2 in cancer tissues (Spearman's correlation coefficient = 0.238 and 0.293; P = 0.013 and P = 0.003, respectively)." (PMID 22479608, 2012). "CXCL1 expression is at a high level in the tumors of many cancers." (PMID 40427171, 2025). "CXCL1 activates the NF-κB pathway, which is crucial for cancer cell survival and inflammation." (PMID 40791849, 2025). "Numerous studies have explored the interaction between CXCL1 and neutrophils in cancer contexts." (PMID 40083557, 2025). "In addition, CXCL1 increases PD-L1 expression on cancer cells, thereby suppressing the activity of cytotoxic lymphocytes." (PMID 40427171, 2025).
cancer (continued). "Topoisomerase inhibitors increase ROS levels in the cell, which leads to the activation of Janus tyrosine kinase 2 (JAK2)-signal transducer and activator of transcription 1 (STAT1) and thus elevated CXCL1 expression, as shown in experiments on many types of cancer." (PMID 40427171, 2025). "However, studies in other cancer cell models have shown that adiponectin can enhance CXCL1 secretion, which in turn promotes VEGF release and angiogenesis." (PMID 41217652, 2025). "During tumorigenesis, cancer cells and associated stromal cells secrete substantial quantities of cytokines (e.g., IL-17A, TGF-β), chemokines (e.g., CXCL1, CXCL2), growth factors (e.g., G-CSF, GM-CSF), as well as lipids, which recruit a large population of neutrophils." (PMID 40342932, 2025). "In addition to reducing the activation of the CXCL1-CXCR2 axis in tumors, this axis can be used as part of anti-cancer therapy using the conjugation of daunorubicin with CXCL1, where CXCL1 serves as a transporter for daunorubicin." (PMID 40427171, 2025). "Cancer therapies often upregulate CXCL1 expression, which in turn drives treatment resistance." (PMID 40427171, 2025). "Cancer cell‐derived CXCL1 also contributes to the recruitment of MDSCs." (PMID 40105652, 2025). "In addition to its role in directly recruiting neutrophils, it has been demonstrated that in cancer, CXCL1 also regulates the expression of CXCR2 on the surface of neutrophils." (PMID 38474145, 2024). "Comprehensive studies on CXCL1’s involvement in colitis-related cancer are relatively rare." (PMID 39582536, 2024). "Additionally, CXCL1 induces the migration of cancer cells, particularly through the induction of epithelial–mesenchymal transition (EMT)." (PMID 38673949, 2024). "Transcription factor CXCL1 expression was frequently upregulated in various cancers." (PMID 38536591, 2024). "CXCL1 is produced in lung tumors not only by cancer cells, but also by fibroblasts." (PMID 38673949, 2024). "Furthermore, several studies have shown a correlation between the overexpression of CXCL1 and poor prognosis in cancer 15-17." (PMID 39132161, 2024). "Significantly, this effect may operate in an autocrine manner, wherein CXCL1 is produced by cancer cells and subsequently acts on the same cells." (PMID 38673949, 2024). "Chemokines play a key role in cancer processes, with CXCL1 being a well-studied example." (PMID 38673949, 2024). "CXCL1 is not only involved in chemotaxis but also plays a critical role in cell activation, proliferation, senescence, and apoptosis, which collectively contribute to its oncogenic potential and complicate its role in cancer pathology." (PMID 39409924, 2024). "Notably, TGF-β1 and CXCL1’s mRNA levels were significantly higher in cancer cells treated with HT-CM." (PMID 39595551, 2024). "CXCL1 induces the proliferation of malignant melanoma cancer cells." (PMID 38673949, 2024). "By targeting CXCL1 or its receptors, it may be possible to inhibit these processes, thereby preventing cancer cells from spreading to other parts of the body." (PMID 39057432, 2024). "Most likely, Fusobacterium promotes the levels of Ki-67, VEGF and CXCL1 proteins in cancer tissues." (PMID 39518144, 2024). "A small subset of mesenchymal genes (CDH2, DKK1, SERPINE2, MATN3, APLP1, CXCL1, FOXC2, BMP1) in Basal BRCA has been validated in this PRC2+-CGI pool with SERPINE2 and CXCL1 being the 2 most commonly overlapping genes found in 7 and 6 cancer types, respectively." (PMID 38902393, 2024). "CXCL1 can induce the proliferation and migration of cancer cells." (PMID 38673949, 2024). "Also, CXCL1 causes an increase in TAM and MDSC, which secrete S100A9 with a pro-survival effect on cancer cells." (PMID 38673949, 2024). "Moreover, CXCL1 exerts an anti-apoptotic effect on cancer cells, which contributes to chemoresistance and radioresistance." (PMID 38673949, 2024).
cancer (continued). "Moreover, there is a lack of available review articles that describe the significance of certain CXCR2 ligands in cancer processes, including CXCL1." (PMID 37408240, 2023). "CXCL1 expression in cancer cells may also depend on pancreatic stellate cells found in a healthy pancreas that are recruited to the cancer niche during pancreatic cancer tumor development." (PMID 37408240, 2023). "The role of CXCL1 in this cancer has been poorly studied; nevertheless, available data suggest that this chemokine may be significant in tumorigenic processes in this cancer." (PMID 37108425, 2023). "CXCL1 expression is also increased by elevated Snail2 expression in cancer cells." (PMID 37408240, 2023). "It has been shown that CXCL1 plays a significant role in various cancer-related processes." (PMID 37108425, 2023). "In HCC tumors, many factors increase CXCL1 expression in cancer cells." (PMID 37408240, 2023). "The focus is on both clinical aspects and the significance of CXCL1 in molecular cancer processes." (PMID 37108425, 2023). "Overall, CXCL1 was elevated in all samples of cancer cell spheroids." (PMID 37445941, 2023). "In addition, activated NF-κB increased C-X-C motif chemokine ligand-1 (CXCL1) expression and secretion by cancer-associated fibroblasts (CAFs) to remodify TME in HNSCC." (PMID 36522474, 2023). "However, there is a lack of comprehensive reviews summarizing the significance of CXCL1 in cancer processes." (PMID 37108425, 2023). "A high level of CXCL1 was found in the HCC cancer tissue compared to normal cells." (PMID 36614235, 2023). "Thus, cancer cells were the main producers of CXCL1, CXCL2, and CXCL8, but cancer cell–intrinsic production of these chemokines was prevented by CALB1 expression." (PMID 37192000, 2023). "Moreover, in women with benign breast lesions, plasma CXCL1 concentrations also remained at similar levels to cancer patients and healthy women." (PMID 37370728, 2023). "Additionally, Fap2 triggers the release of proinflammatory cytokines, namely IL-8 and C-X-C motif chemokine ligand 1 (CXCL1), which enhances the migration of cancer cells." (PMID 38029267, 2023). "Furthermore, three pairs of CXCL gene-immune cell interactions (CXCL13-CD8+ T cells, CXCL9/10-M1 cells, CXCL1/2/3/8-neutrophils) were identified through single-cell and pan-cancer analysis." (PMID 37540227, 2023). "Interestingly, a recent report also showed that IL-8, CXCL1, and CXCL2 secreted by cancer-associated mesenchymal stromal cells can promote the polarization of TAMs." (PMID 36411463, 2022). "In addition to increasing proliferation, CXCL1 also induces cancer cell migration, particularly EMT." (PMID 35054978, 2022). "Cancer cells that overexpress CXCL1 and 2 are primed for survival in metastatic sites." (PMID 35158784, 2022). "The regulation of CXCL1 expression by TGF-β is an important mechanism observed in cancer." (PMID 35054978, 2022). "Having shown that CXCL1 enhances cancer cell invasion, we asked whether inhibition of the CXCL1 receptor CXCR2 blocked the macrophage-induced invasion." (PMID 35998057, 2022). "Owing to the pivotal role of CXCL1 in cancer progression, we focused on CXCL1 for further study." (PMID 35183163, 2022). "Next, we isolated BMDMs from WT or KLK6−/− mice to investigate whether macrophages affect KLK6-mediated CXCL1 expression in cancer cells." (PMID 36552865, 2022). "It has been recognized that several types of human cancers constitutively express CXCL1, which may serve as a crucial mediator involved in cancer development and metastasis via an autocrine and/or paracrine fashion." (PMID 35764974, 2022). "In addition, activation of CXCR2 by CXCL1 was observed to facilitate cancer cell migration and invasion in oral squamous carcinoma." (PMID 36612163, 2022).